SPSB2 (splA/ryanodine receptor domain and SOCS box containing 2)
Description:
Substrate recognition component of a SCF-like ECS (Elongin BC-CUL2/5-SOCS-box protein) E3 ubiquitin-protein ligase complex which mediates the ubiquitination and subsequent proteasomal degradation of target proteins. Negatively regulates nitric oxide (NO) production and limits cellular toxicity in activated macrophages by mediating the ubiquitination and proteasomal degradation of NOS2. Acts as a bridge which links NOS2 with the ECS E3 ubiquitin ligase complex components ELOC and CUL5.
Synonyms: SSB-2; GRCC9; SSB2; LOC105369632
Tractability: Small molecule: a high-quality ligand is known. PROTAC: a small molecule that binds it is known.
Gene: Protein-coding gene on chromosome 12 (6,870,934 to 6,889,358, reverse strand). Ensembl gene ENSG00000111671.
Subcellular location: Cytoplasm; Cytoplasm, cytosol
Pathways (Reactome):
Immune System: Antigen processing: Ubiquitination & Proteasome degradation
Metabolism of proteins: Neddylation
Gene Ontology:
Molecular function: protein binding; ubiquitin-like ligase-substrate adaptor activity
Biological process: protein ubiquitination; ubiquitin-dependent protein catabolic process; proteasome-mediated ubiquitin-dependent protein catabolic process; intracellular signal transduction
Cellular component: cytosol; SCF ubiquitin ligase complex; cytoplasm
Genetic constraint (gnomAD): Loss-of-function variants: 26 observed, 22.03 expected, observed/expected ratio (o/e) 1.18, 90% interval 0.86 to 1.63. The upper end of that interval is the gene's LOEUF score, 1.63, which puts it in group 6 of 6, group 1 being the genes least tolerant of losing a copy. Missense variants: 413 observed, 354.18 expected, observed/expected ratio (o/e) 1.17, 90% interval 1.08 to 1.26. Synonymous variants: 153 observed, 157.99 expected, observed/expected ratio (o/e) 0.97, 90% interval 0.85 to 1.11.
Homologues: Orthologues: chimpanzee SPSB2 (99% identical), dog SPSB2 (95% identical), rabbit SPSB2 (95% identical), pig SPSB2 (95% identical), mouse Spsb2 (90% identical), macaque SPSB2 (90% identical), rat Spsb2 (81% identical), guinea pig SPSB2 (73% identical), Drosophila melanogaster gus (50% identical), Caenorhabditis elegans spsb-1 (43% identical), Caenorhabditis elegans spsb-2 (41% identical), zebrafish SPSB2 (33% identical). Paralogues in human: SPSB4 (53% identical), SPSB1 (52% identical), FBXO45 (33% identical), SPSB3 (23% identical).
Diseases named in the same sentence as SPSB2 in open-access papers:
SPSB2 is named in the same sentence as 12 diseases in open-access papers, as found by Europe PMC text mining. Sharing a sentence is not in itself a finding about the gene and the disease. The quoted sentences say what the papers report.
hepatocellular carcinoma (2 papers, 2019 to 2025). A malignant tumor that arises from hepatocytes. "Inhibition of SPSB2 expression effectively attenuated the proliferative viability of the two hepatocellular carcinoma cell lines and reduced the cells’ metastatic and invasive abilities." (PMID 40149497, 2025). "As a result, this research aimed to explore the connection between SPSB2, immune cell infiltration, and the prognosis of patients with hepatocellular carcinoma." (PMID 40149497, 2025). "Collectively, these data demonstrated that SPSB2 significantly inhibits HCV replication in hepatoma cells, and this effect is dependent on its SOCS box." (PMID 31344133, 2019). "Exogenous expression of SPSB2 in hepatoma cells decreased HCV RNA and protein levels which depended on the SOCS box, while knockdown of endogenous SPSB2 increased HCV RNA and protein levels." (PMID 31344133, 2019). "The expression of SPSB2 was higher in hepatocellular carcinoma cells than in normal hepatocytes." (PMID 40149497, 2025).
asthma (1 paper, 2021). "The proteins encoded by the candidate genes identified in our study are iNOS, SPSB2, and RIPOR2, all of which have functions that could influence the levels of FeNO and the phenotypes of obstructive airway diseases including asthma and COPD." (PMID 34782693, 2021).
non-small cell lung carcinoma (1 paper, 2025). A group of at least three distinct histological types of lung cancer, including non-small cell squamous cell carcinoma, adenocarcinoma, and large cell carcinoma. "A recently identified gene, SPSB2, has been implicated in cell signaling, impacting the development and progression of non-small cell lung cancer." (PMID 40149497, 2025). "Several studies have shown that SPSB2 is a target gene of ETV4 and is connected with tumor invasion and dependent growth, as well as dismal prognosis in non-small cell lung cancer." (PMID 40149497, 2025).
cancer (3 papers, 2019 to 2025). A tumor composed of atypical neoplastic, often pleomorphic cells that invade other tissues. "Among the genes closely related to SPSB2 expression, CDC45, RAD51, TRIP13, MYBL2, and CDC20 play essential roles in cancer development." (PMID 40149497, 2025). "In the present study, we first found that SPSB family proteins SPSB2 and SPSB3 inhibit HCV replication, in addition to their other roles in cellular immune response and cancer invasion and metastasis." (PMID 31344133, 2019).
infection (1 paper, 2019). The state of being infected such as from the introduction of a foreign agent such as serum, vaccine, antigenic substance or organism. "As an adaptor protein, it can regulate the host’s response to infection, but little is known about whether SPSB2 plays a role in HCV replication." (PMID 31344133, 2019). "Also, to assess whether SPSB2 affects NS5A stability in an authentic infection system, Huh7 cells were infected with JFH-1 (MOI = 0.1) after transfected with the indicated plasmids." (PMID 31344133, 2019). "SPSB1, SPSB2, and SPSB4 can interact with inducible nitric oxide synthase (iNOS) resulting in its proteasomal degradation to regulate the host’s response to infection." (PMID 31344133, 2019). "Next, SPSB2 mRNA and protein levels were measured at various time points after infection with JFH-1 (MOI = 1); the results showed that SPSB2 mRNA and protein levels were upregulated 4 and 6 days after infection." (PMID 31344133, 2019). "However, due to lack of HCV JFH-1 E1 antibody, the interaction between SPSB2 and E1 in the HCV infection system could not be further explored." (PMID 31344133, 2019).
tumor (1 paper, 2025). "Our study’s outcomes indicate that SPSB2 is strongly linked to immune cell infiltration and immunosuppression within the tumor microenvironment of LIHC." (PMID 40149497, 2025). "Our research indicates that elevated SPSB2 expression might be linked to gene mutations and tumor proliferation, invasion, and metastasis in patients with LIHC." (PMID 40149497, 2025). "To assess the impact of SPSB2 on the tumor microenvironment, we employed the ssGSEA method for immune infiltration analysis." (PMID 40149497, 2025). "SPSB2 potentially contributes to tumor formation by regulating immune-related signaling pathways and facilitating immune cell infiltration." (PMID 40149497, 2025). "To gain a deeper insight into the molecular mechanism of SPSB2 in tumor initiation and progression, we conducted GO, KEGG, and GSEA functional enrichment analyses with SPSB2 and its associated differentially expressed genes." (PMID 40149497, 2025). "Consequently, SPSB2 can serve as a molecular target for tumor treatment." (PMID 40149497, 2025). "SPSB2’s family member, SPSB1, interacts with TβRII through its SPRY structural domain and promotes the degradation of TβRII, thus negatively regulating TGF-β signaling and inhibiting tumor cell migration and invasion." (PMID 40149497, 2025).
SPSB2 also shares sentences with these, for which no sentence is quoted: Anxiety (1 paper); Borderline personality disorder (1); cerebellar ataxia (1); colorectal cancer (1); infectious disease (1); Sepsis (1).